WEE1 (WEE1 G2 checkpoint kinase)
Diseases named in the same sentence as WEE1 in open-access papers (continued):
Sharing a sentence is not in itself a finding about the gene and the disease.
cancer (continued). "Here, we review evidence of investigations into inhibitors of two important proteins (Chk1 and Wee1) and how these can be used to increase the effectiveness of radiotherapy in cancer treatment." (PMID 39272874, 2024). "This study revealed a role of Wee1 in ensuring accurate segregation of chromosomes during mitosis, and thus provided a basis for a new principle of cancer treatment with Wee1 inhibitors." (PMID 38166399, 2024). "For example, in small cell lung cancer (SCLC), a WEE1 inhibitor induced DNA damage in cancer cells, increasing type I interferons, CCL5 and CXCL10 via activation of the cGAS-STING pathway, enhancing the response to PD-L1 blockade." (PMID 38796460, 2024). "Treatment of the cell lines with varying concentrations of adavosertib, a WEE1 inhibitor, and measurement of the area of the cancer cell-occupied region using IncuCyte Zoom (Ver." (PMID 39335109, 2024). "In recent years, targeting WEE1 kinase has attracted great interest in cancer therapy, and clinical trials of WEE1 inhibitors as monotherapies or combination chemotherapies are ongoing in patients with refractory solid tumours." (PMID 38365687, 2024). "Wee1 is a G2 checkpoint kinase and prevents entry into mitosis following DNA damage in cancer cells." (PMID 39622844, 2024). "Subsequent drug screening shows WEE1 inhibition synergistically destroys cancer cells with hyperthermia." (PMID 38453961, 2024). "The overexpression of CHK1 and WEE1 in cancer cells provides them with a survival advantage over cells with normal expression levels." (PMID 38606093, 2024). "WEE1 inhibitor has been shown to sensitize cancer cells to cytotoxic agents, and WEE1 inhibition can reduce HR activity by directly constraining BRCA2." (PMID 39175540, 2024). "This nevertheless highlights that the ability of Wee1 inhibition to overcome the inherent radioresistance of cancer stem cell populations requires further elucidation." (PMID 39272874, 2024). "The overexpression of Wee1 has been observed in malignant tumor cells, including hepatic cell carcinomas, breast cancers, glioblastoma, respiratory tumors, and gastrointestinal tumors." (PMID 39464635, 2024). "Inhibition of Wee1 is expected to force cancer cells undergoing DNA replication or repair to enter mitosis, resulting in cell death through mitotic catastrophe." (PMID 38166399, 2024). "In a multi-omics characterization of RMS, Wee1 was found to be more highly expressed at the mRNA level in RMS relative to other pediatric cancers with resultant dysregulation of the G2/M pathway." (PMID 38730598, 2024). "Overexpression of CHK1 and WEE1 has been reported in the setting of cancer and has been shown to aid in the growth and development of tumors." (PMID 38606093, 2024). "For now, Chk1 and Wee1 remain important cancer targets for radiosensitisation, but they need further experimental exploration." (PMID 39272874, 2024). "Accumulating evidence indicates that aberrant WEE1 expression holds prognostic value in various cancers." (PMID 38169513, 2024). "Our experiments provide novel insights into functional ability of the combination of CHK1 and WEE1 inhibitors to repair DNA and strengthen the case of exploring the combination in cyclin E overexpressing cancers in clinical trials." (PMID 39516567, 2024). "For instance, a comprehensive comparison of 34 cancer-versus-normal data sets, revealed increased expression of WEE1 mRNA in 77% of the samples." (PMID 38231277, 2024).
cancer (continued). "For instance, HDAC6 inhibitors have been demonstrated to enhance the sensitivity of cancer cells to various chemotherapeutic agents such as temozolomide, gemcitabine, oxaliplatin, eribulin, WEE1 inhibitor adavosertib, 5-FU, and imatinib." (PMID 39063958, 2024). "This is because cancer cells often show elevated replication stress, which likely provides sensitivity to WEE1 inhibitors." (PMID 39273409, 2024). "WEE1 has a role in regulating the cell cycle by modulating the initiation of cell division, making it a potential target for treatments in cancer therapy." (PMID 38961104, 2024). "WEE1 represents an attractive target for cancer therapy as WEE1 inhibition exploits cancer cell reliance on the G2/M checkpoint and exacerbates replication stress to intolerable levels." (PMID 36632060, 2023). "WEE1 inhibition in cancer cells with high levels of replication stress results in induction of replication catastrophe and mitotic catastrophe." (PMID 37292855, 2023). "Clinical trials with AZD6738, an ATR inhibitor, and AZD1775 (NCT02617277), a WEE1 inhibitor, individually as well as in combination with durvalumab in patients with advanced cancers, are currently ongoing." (PMID 36900418, 2023). "Studies have shown that WEE1 is overexpressed in various cancer cell types, including cervical cancers, lung cancers, breast cancers, squamous cell carcinoma, glioblastoma, and melanoma." (PMID 37958890, 2023). "WEE1 inhibition has emerged as a strategy to eliminate cancer cells; however, adverse effect concerns have warranted further preclinical investigations." (PMID 37325550, 2023). "This study investigates a previously unreported combination of the cIAP and WEE1 inhibitor drug classes, which target pathways known to be dysregulated in and critical for cancer cell survival and progression." (PMID 36831373, 2023). "As a critical gatekeeper of the G2-M checkpoint and key regulator of genomic integrity during S-phase, WEE1 represents a promising target for the development of anti-cancer therapeutic strategies." (PMID 37715172, 2023). "A genome-wide CRISPR screen of 563 cancer cell lines revealed that WEE1 was crucial for the viability of nearly all the cancer cell lines and that WEE1 was frequently overexpressed in both solid and hematologic malignancies." (PMID 37370065, 2023). "Genetic studies demonstrated that transcriptional regulation of WEE1 and p21 cooperatively contributes to cancer cell proliferation promoted by BMAL1::CLOCK." (PMID 36937362, 2023). "Since upregulation of Myt1 is a barrier towards cancer cell killing by G2/M checkpoint inhibitors, Myt1 inhibition is a potential step to subvert the resistance to Wee1 inhibition." (PMID 38020882, 2023). "Secondly, and importantly for cancer therapy, the upregulation of Cdk1 activity by Wee1 inhibition can force cancer cells to enter mitosis with under-replicated or unrepaired chromosomes leading to mitotic catastrophe and chromosome fragmentation." (PMID 38020882, 2023). "Adavosertib inhibits Wee-1 pathway, which forces cancer cells to prematurely enter mitosis, while also impairing DNA damage repair, and consequently promoting cell death." (PMID 37705995, 2023). "Given that ARID1AMUT cancers are known to have defects in S and G2/M, WEE1 inhibitors (WEE1i) are also a rationale therapeutic approach to exploit ARID1AMUT CCOC36,37." (PMID 37841875, 2023). "Inhibition of WEE1 has become an attractive target for cancer therapy due to the simultaneous induction of replication stress and inhibition of the G2/M checkpoint." (PMID 37292855, 2023).
cancer (continued). "Cancer cells are reliant on WEE1-activated G2/M checkpoint to cope with DNA damage and avoid apoptosis." (PMID 36595671, 2023). "DDR kinase inhibitors, such as those targeting PARP, ATM, ATR, DNA-PK, CHK1/2, BER, and WEE1, have been tested in clinical trials as a way to kill tumor cells, as cancer cells are more sensitive to compromised repair systems compared to normal cells." (PMID 36900418, 2023). "As a result, cancer cells rely on WEE1 activity to initiate G2/M arrest and to provide time for DNA damage repair." (PMID 37510250, 2023). "AZD1775 (also known as adavosertib) represents a potent WEE1 inhibitor under investigation in a variety of cancer types in combination with chemoradiotherapy." (PMID 36831373, 2023). "Inhibitors of cell cycle checkpoints such as CHK1 and WEE1 can also eliminate HRD cancers by pushing cancer cells through the cell cycle despite unrepaired DNA damage and causing death by mitotic catastrophe." (PMID 36929572, 2023). "Taken together, these results demonstrate the potential for combined IAP and WEE1 inhibition to exert anti-cancer activity and sensitize HNSCC cells to TNFα-induced cytotoxicity." (PMID 36831373, 2023). "Rapidly proliferating cancer cells exhibit genetic instability and amass cumulative DNA damage that requires WEE1 and an intact checkpoint for adequate repair." (PMID 36831373, 2023). "Although, most studies aim to specifically exploit the role of WEE1 in the G2/M checkpoint, evidence has emerged that the S phase impacts of WEE1 inhibition contribute to cancer-specific lethality." (PMID 36632060, 2023). "Collectively, our observations support the concept that anti-apoptosis activity of the cancer-specific WEE1 contributes to BMAL1::CLOCK stimulated HCC cell proliferation." (PMID 36595671, 2023). "WEE1 inhibition has received a lot of attention in the last decade as a promising treatment for cancers, including hematologic malignancies, since it regulates the cell cycle." (PMID 37370065, 2023). "The combination of Wee1 blockade with cisplatin has shown synergistic efficacy in several types of cancers, but little is known regarding UC." (PMID 37296592, 2023). "Here, we report the combinatorial drugging of PKMYT1 and WEE1 kinases, which synergistically eradicates cancer cells already at low drug dose." (PMID 37325550, 2023). "The loss of G1 control, a common feature in cancer, and increased RS in tumours both result in dependency on ATR, CHK1 and WEE1 signalling, making these kinases attractive targets for cancer therapy." (PMID 36606678, 2023). "Inhibition of Wee1 abrogates the extended pause in the G2-M catapulting cancer cells into a mitotic catastrophe and apoptosis." (PMID 37633054, 2023). "It has been reported that the inhibition of Chk1, Chk2 or Wee1, as monotherapy or in combination with DNA damaging agents, induces apoptosis in several cancers, including hematological malignancies." (PMID 38125947, 2023). "Accordingly, Wee1 inhibition reconstitutes CDK1 activity to reverse resistance of these cancer cells to immune attack." (PMID 36106115, 2022). "Newest research on WEE1, has once more pinpointed the efficacy of WEE1 inhibitors in combination with genotoxic stress as approach in cancer treatment." (PMID 35902728, 2022). "Only a few studies have examined the efficacy of Wee1 inhibition – alone or in combination - in the eradication of cancer stem cells." (PMID 35251998, 2022). "It displayed anti-cancer manifestations such as cell proliferation suppression and cell cycle arrest when the aberrant overexpression of Wee1 was knocked down in CML cells." (PMID 36575478, 2022).
cancer (continued). "This is the first study to display the potential of utilizing the combined inhibition of DDK and WEE1 for the treatment of cancer." (PMID 36338546, 2022). "Among these candidate genes, WEE1 was selected as a potential target gene because it has been shown to be involved in the regulation of multiple functions in various cancer types." (PMID 35127343, 2022). "CHEK1 and WEE1 activation is required to initiate cell cycle arrest to give cancer cells enough time to recover from damage accrued from therapeutic agents." (PMID 35301276, 2022). "In conclusion, Wee1 inhibitors show great potential to make an impact in the clinic for the therapy of several cancer types." (PMID 35251998, 2022). "The key role of Wee1 in regulating the G2/M checkpoint in response to DNA damage has made it an attractive target for cancer therapy." (PMID 35251998, 2022). "Recently, many studies have shown that WEE1 is upregulated in numerous tumors and plays a cancer-promoting role." (PMID 35127343, 2022). "On the other hand, overexpression of WEE1 in cancer strengthens G2/M checkpoint for DNA damage response and thereby supports cell proliferation." (PMID 35902728, 2022). "As most cancer therapies aim to induce lethal amounts of DNA damage in cancer cells, Wee1 overexpression promotes cancer cell survival (and resistance) by reinforcing DNA damage checkpoints and preventing mitotic catastrophe." (PMID 35251998, 2022). "Both phase I and phase II clinical trials have suggested that AZD1775, a Wee‐1 inhibitor, as monotherapy or in combination with chemotherapy has high efficacy in treating different cancers, with a well‐tolerated cytotoxic profile." (PMID 35393784, 2022). "We identify approaches to exploit this effect by co-inhibiting checkpoint kinases CHK1 or WEE1 to induce cancer cell death through replication catastrophe." (PMID 34773074, 2022). "Cancer cells driven by oncogenes are hyperdependent upon the ATR/CHK1/WEE1 signaling pathway, which enables them to attenuate RS." (PMID 36253861, 2022). "WEE1 overexpression abrogates immune cell killing, for example by protecting cancer cells from granzyme B/TNFα induced cell death." (PMID 36276148, 2022). "CHEK1 and WEE1 are cell cycle proteins whose expression is commonly dysregulated in multiple cancer types." (PMID 35301276, 2022). "MK1775 is a WEE1 inhibitor and has been reported to be included in clinical trials on DNA-damaging therapies in various cancer types." (PMID 36497337, 2022). "As a G2/M phase checkpoint kinase and a DNA damage repair checkpoint kinase engaged in the DNA damage response (DDR), along with an oncogenic driver present in various cancers, the particular involvement of Wee1 in DNA damage is far from clear." (PMID 36575478, 2022). "At present, cell cycle checkpoint inhibitors (ATR, CHK1 and WEE1) have been already an general and effective measure for anti-cancer therapy." (PMID 35021154, 2022). "Along with PARPs, Wee1 is considered a useful player to target in cancer cells, since it specifically controls the G2/M checkpoint, and helps malignant cells to maintain a sustainable degree of genomic instability." (PMID 35563769, 2022). "WEE1 is a nuclear kinase that is upregulated in many cancers and is proposed as a target for anticancer therapy." (PMID 35572733, 2022). "An example of a successful attempt to establish a fateful triangle for cancer cells in a conditional synthetic lethality approach is the combination of inhibitors of Wee1 and of the kinase Ataxia telangiectasia and Rad3 related (ATR)." (PMID 35251998, 2022). "Drawn from observational works, WEE1 depletion attacks the proliferative ability of CC cells and has the potency to reverse G2/M cell cycle checkpoint activation in cancers." (PMID 35477702, 2022).
cancer (continued). "The ataxia telangiectasia and Rad3-related (ATR) and WEE1 kinases play roles in protecting cancer cells from high replication stress and in regulating the remaining cell cycle checkpoints." (PMID 34359691, 2021). "Inhibitors of ATR or WEE1 therefore have the potential to selectively kill cancer cells and are currently being tested in clinical trials." (PMID 34359691, 2021). "The ataxia telangiectasia and Rad3-related (ATR) and WEE1 kinases are two key players in DNA damage and replication stress response, and both kinases are considered promising targets for cancer treatment." (PMID 34359691, 2021). "ETC-168 can be used as a useful compound and surrogate tool to block oncogenic expression of E2F1, FOXM1, and WEE1 in human cancers." (PMID 33564073, 2021). "Inhibitors of other components of the intra-S phase and G2 phase DNA damage checkpoints, such as ATR and Wee1, are also in clinical trials for the treatment of cancer." (PMID 34372559, 2021). "It has been proposed that WEE1 inhibitor promotes cancer cells to prematurely enter mitosis as a result of bypassing the G2 cell-cycle checkpoint as well as delays mitotic exit, resulting in mitotic arrest." (PMID 34269904, 2021). "In several cancer types, WEE1, which is the gatekeeper of the G2 arrest, is expressed at high levels, and its inhibition sensitizes cancer cells to DNA-damaging agents by compromising the G2-M checkpoint." (PMID 34946644, 2021). "So the synergism between WEE1 inhibition and H3K36me3 deletion promotes cancer cell lines like A498, LB996, U2OS, and the xenografts from these cells to death." (PMID 34715919, 2021). "Firstly, pointing toward a likely synergy between WEE1 and ATR inhibitors, several previous studies have shown synergistic effects on cancer cell killing when the WEE1 inhibitor MK1775 is combined with inhibitors of CHK1, a major downstream effector of ATR." (PMID 34359691, 2021). "Wee1 downregulation in cancer tissues was observed in most of them, suggesting a tumor suppressor role for Wee1." (PMID 34639030, 2021). "Inhibiting Wee1 has been a strategy for cancer targeted therapies, where it has been shown to be effective." (PMID 33498235, 2021). "Promoted RS rates in cancer cells make the ATR/CHK1/WEE1 kinases a suitable target for anticancer therapy." (PMID 33672884, 2021). "While these data indicate that Wee1 acts as a tumor suppressor, several studies highlighted an increased expression of Wee1 in several types of cancer." (PMID 34639030, 2021). "SLFN11 informs on the standard of care chemotherapy based on DDA and the effect of selected combinations with ATR, WEE1 or CHK1 inhibitor in a wide range of cancer types and models." (PMID 33339894, 2021). "WEE1 is an attractive target for cancer therapies including for TNBC, and strategies are being intensively explored in preclinical studies and clinical trials." (PMID 33552868, 2021). "Since recent studies have demonstrated that inhibition of WEE1 can lead to mitotic catastrophe and apoptosis in cancer cells, we next examined the effects of WEE1 overexpression and knockdown on apoptosis in ESCs." (PMID 34686198, 2021). "Cancer cells often show mutations in protein kinases (CDK2, CDK4, CDK6, chk1, Wee1 and PLK1) involved in cell proliferation." (PMID 35366261, 2021). "Under this circumstance, cancer cells become highly dependent on WEE1‐mediated G2/M checkpoint control for DNA repair." (PMID 34977872, 2021). "WEE1, a member of the Serine/Threonine protein kinase family, is upregulated and possesses oncogenic functions in several cancer types." (PMID 33986660, 2021). "Drug resistant cancer cells exhibited collateral sensitivity to the Wee-1 inhibitor, adavosertib (AZD1775)." (PMID 34123801, 2021).